RNU6-1287P (RNA, U6 small nuclear 1287, pseudogene)
Gene: Small nuclear RNA gene on chromosome 15 (56,274,530 to 56,274,636, reverse strand). Ensembl gene ENSG00000199784.
Homologues: Orthologues: chimpanzee U6 (100% identical), macaque U6 (97% identical), guinea pig U6 (73% identical). Paralogues in human: RNU6-797P (93% identical), RNU6-1091P (90% identical), RNU6-1047P (88% identical), RNU6-500P (88% identical), RNU6-727P (88% identical), RNU6-744P (88% identical), RNU6-944P (88% identical), RNU6-1060P (87% identical), RNU6-1243P (87% identical), RNU6-188P (87% identical), RNU6-1083P (86% identical), RNU6-1309P (86% identical), and 1287 more.